TNF (tumor necrosis factor)
Diseases named in the same sentence as TNF in open-access papers (continued):
Sharing a sentence is not in itself a finding about the gene and the disease.
tumor (continued). "Indeed, the TNF-α and TGF-β1 secreted by MSCs increased tumor cell EMT in colon carcinoma cells via the activation of the p38 MAPK and ERK signaling pathways." (PMID 37686315, 2023). "Inhibited tumor growth.Enhanced tumor immune response.Increased the number of tumor-infiltrating M1 macrophages and dendritic cells.Enhanced the secretion of IL17A in spleen.Increased the level of TNF-α in tumor." (PMID 37242947, 2023). "However, only PEPT CAR-T cells displayed lower levels of IFN-γ, TNF-α, and IL-2 release compared to 2G CAR-T cells when challenged with CD19 + PDL1- tumor cells." (PMID 37777797, 2023). "According to the scRNAseq results, IFNγ and IL1β/TNFα are necessary to induce the highest levels of NOS2 and COX2 expression, which suggests that lymphoid cells could be a contributing factor in the tumor." (PMID 37169743, 2023). "Indeed, it has already been reported that the CD95L-CD95 system contributes to AICD of tumor infiltrating CD8+ T cells in anti-PD1/anti-CTLA-4 treated mice, opening the possibility that TNF and CD95L act in this scenario in a redundant fashion." (PMID 38020877, 2023). "Some polysaccharides can activate host immune cells and further promote the secretion of a variety of inflammatory cytokines, such as interleukin‐6 (IL‐6), IL‐1β, and tumor necrosis factor TNF‐α, thus exhibiting significant immunomodulatory and anti‐tumor effects." (PMID 38268870, 2023). "In addition, pDCs directly induce tumor cell lysis via secreting cytotoxic cytokines including granzyme B (GZMB), TNF-α, and soluble TRAIL85." (PMID 37817484, 2023). "Their inflammatory activity involves various inflammatory molecules such as IL-1, IL-12 and IL-23, TNFα, and chemokine ligands (CXCL5, CXCL9 and CXCL12) as well as tumor-specific antigen presentation via major histocompatibility complex molecules (MHC class 1 and 2)." (PMID 38164130, 2023). "This found that after 10 days of inoculation of the tumor in the paw and peritoneum, treatment with the resin oil significantly reduced ascites volume and inhibited the increase of inflammatory mediators such as PGE2, nitric oxide and TNF in the fluid." (PMID 36839993, 2023). "Our data from KEGG showed that five signaling pathways, including IL-17, HIF-1α, TLR4, NF-κB p65, and TNF signaling, may be the therapeutic pathways in the DOKD treatment of tumor development." (PMID 37239383, 2023). "Th1 cytokines and cytotoxic mediators are essential for T cells to maintain the GVL effect and kill tumor cells, yet they also lead to the damage of healthy host tissues, More specifically INF-γ and TNF-α secretion by donor CD4 T cells are the hall mark of persistence of GvHD mediators." (PMID 36901757, 2023). "For example, strawberry (Fragaria ananassa) methanolic extracts have anti-inflammatory activity, reducing the levels of the tested inflammatory markers (NF-kB, pIkBa, TNF-α, IL-1b, IL-6, and iNOS) in RAW macrophages, which is an Abelson murine leukemia virus-induced tumor." (PMID 36771154, 2023). "Tumor necrosis factor alpha (TNF-α) is one of the pro-inflammatory cytokines found in cancer patients and is reported to be involved in the immune system as well as in the surveillance of tumor growth." (PMID 36765695, 2023). "In addition to the tumor, we measured the expression profile of pro-inflammatory cytokines (IFN-γ, IFN-β, TNF-α, IL-12, and IL-6) in the spleen tissue as the main secondary host lymphoid compartment." (PMID 37901237, 2023). "Together, these data warrant future studies addressing whether disruption of the local IL-1α/TNFα axis can impede EMH and how cell products of EMH induced by IL-1α and LIF impact the tumor microenvironment and cancer outcomes." (PMID 37134077, 2023).
tumor (continued). "While data here clearly demonstrate that maximum human NOS2 expression is induced by IFNγ, IL1β, and TNFα, identical to that in murine tumor cells, human macrophages do not activate NOS2 with IFNγ or LPS." (PMID 37169743, 2023). "Irradiated tumor tissues and cancer cells recruit chemokines such as CCL22 and CXCL12 and produce a range of cytokines such as TNF-α, TGF-β, IL-1, IL-6, and GM-CSF which could recruit tumor-infiltrating lymphocytes (TILs) into radiation site." (PMID 37259456, 2023). "Such as MTX, Anti-TNF agents, or other biologics, did not induce tumor or hematological malignancies." (PMID 37182186, 2023). "Skin TNF-α is produced as a proinflammatory cytokine in response to ultraviolet B radiation (UVB) to facilitate UVB-induced apoptosis and therefore contributes to remove the damaged cells and thus diminishing tumour genesis." (PMID 36980727, 2023). "In contrast, higher concentrations of TNFα did not result in an increase in tumor growth or a clear decrease in cell proliferation." (PMID 36996146, 2023). "Especially, IL-1β may induce IFN-γ production, while TNF-α and IFN-γ can kill tumor cells and inhibit tumor growth directly." (PMID 37951973, 2023). "Importantly, the overexpression of circCRIM1 suppressed the immune evasion of NSCLC and promoted the expressions of Granzyme B, IFN-γ, and TNF-α of CD8+ T and NK cell in vitro co-culture assays and tumor xenograft models." (PMID 36672208, 2023). "In addition, overexpression of DSE promoted the overexpression of tumor killer molecules such as GZMB, TNF and IFNG in CD8 + T cells, and inhibited the expression of inhibitory molecules such as PD-1, TIM-3 and LAG-3." (PMID 37833287, 2023). "The deletion of PTPN2 in T cells not only promoted the activation and cytotoxic potential of tumor-infiltrating/resident T cells (as reflected by IFNγ, TNF and GZMB levels), but also enhanced STAT-1 signaling in AT3-OVA tumor cells, the expression of Cxcl9 and the recruitment of T cells." (PMID 37500611, 2023). "In the tumor grading analysis, IL-1β and TNF-α did not present significantly different values in patients with G1, G2, and G3 tumors; therefore, these cytokines cannot be taken into account in the prediction of grading in patients diagnosed with CRC." (PMID 38137862, 2023). "Moreover, with DP treatment, CD8+ naive T-differentiated terminal Tex, after persistent tumor antigen stimulation in vitro, produced more IFN-γ and TNF-α compared with anti–PD-1-treated terminal Tex." (PMID 36853831, 2023). "In addition, neutrophils can also secrete bioactive substances that promote tumor progression, including VEGF, MMP9, Oncostatin M (OSM), IL-1β, ​​TNF-a, IL-8, CXCL3, ROS." (PMID 37644468, 2023). "Moreover, USP14 expression is induced by TNF-α, forming a feedback loop with JNK and leading to tumor amplification." (PMID 36693850, 2023). "CD8 T cells directly kill tumor cells by secreting perforin and granzymes and facilitating antitumor immune responses by the production of IFN-γ and TNF, which activate local APCs and increase the immunogenicity of tumor cells by inducing MHC expression and activation of immunoproteasomes." (PMID 38258065, 2023). "TNF-α and IFN-γ expression levels remained unchanged and were comparable to control levels on the fourth and seventh days, but IL-2 levels increased greatly on the seventh day after Ce6-PDT therapy, mimicking the pattern as seen in the tumor." (PMID 36835310, 2023). "Proinflammatory cytokines (TNF-α, IL-β, and IL-23) released by M2-type TAMs in solid tumors continue induce overexpression of PD-L1, CTLA4, and glucocorticoid-induced TNF receptor family-regulated protein (GITR) to inhibit tumor immunity." (PMID 37880233, 2023). "Additionally, group 5 had the greatest levels of TNF-α and IFN-β, demonstrating a systemic immune response against the tumor." (PMID 37762239, 2023). "In addition, blocking STAT1 inhibits the secretion of TNF-α and IFN-γ by immune cells, leading to tumor growth and metastasis." (PMID 36865498, 2023).
tumor (continued). "Furthermore, CRC tumor cells also produce TNFR2 on their surface, which interacts with TNF-α and promotes tumor cell proliferation in TME." (PMID 36672682, 2023). "Hence, we collected T cells co-cultured with tumor cells at an E:T of 1:5 for 48 h and then detected the release of IFN-γ and TNF-α from CAR-T cells using flow cytometry." (PMID 37149721, 2023). "Using the terminal deoxynucleotide transferase dUTP nick end labeling (TUNEL) assay to detect apoptotic DNA fragmentation in tumor sections, we found that combination of RGD4C.TPA.TNFα with CDDP induced the highest level of apoptosis compared to CDDP or RGD4C.TPA.TNFα alone." (PMID 37331004, 2023). "GSVA revealed that cell cycle-related pathways (e.g., MYC target and G2/M checkpoint), immune response pathways (e.g., IL-2 STAT5 signaling and TNF signaling via NF-κB), and aberrantly activated pathways (e.g., mTORC1 and PI3K/AKT/mTOR signaling) were dominant in tumor cells of APHC." (PMID 37336873, 2023). "Moreover, reduced IFN and TNF production was observed in primary NK cells after treatment with the TRPML1 antagonist, ML-SI3, at 10 and 50 μΜ, followed by K562 tumor cell challenge." (PMID 37737664, 2023). "In the secondary tumors, we also found a higher frequency of tumor-infiltrating CD8 + T cells in the TILs and a higher frequency of CD8 + T cells expressing TNF-α and IFN-γ in the combination treatment group than in the individual anti-TIGIT or RT groups (data not shown)." (PMID 35794399, 2023). "Furthermore, the combination of TH-302 NPs with α-PD-1 significantly promoted the levels of TNF-α, IFN-γ, and granzyme B in tumour tissues." (PMID 37993847, 2023). "Notably, Cluster 1, 2, and 4 showed better response to ICIs, which should be due to TME supporting anti-tumor immunity, including IL6/JAK/STAT3 signaling, tumor necrosis factor (TNFA, TGFB) and interferon (IFNA, IFNG) pathways." (PMID 36817452, 2023). "In addition, co-culturing of CD8+ T cells with tunicamycin pre-treated Ero1aKO tumor cells showed significant increase in the release of IFN-γ, TNF-α, and GzmB compared with controls, indicating that tumor ERO1A induces T cell dysfunction." (PMID 37769655, 2023). "Furthermore, it can increase the production of CD8+ T lymphocytes and immune factors (IL-2, TNF-α, and IFN-γ), thereby improving T cell recognition and the killing of tumour cells." (PMID 37514054, 2023). "Furthermore, increased sHLA-E was detected in various different tumour cell culture supernatants and was proved to be upregulated by various cytokines, such as IFN-γ, IFN-α and TNF-α." (PMID 37901227, 2023). "Intradermally injected SCCNVs could deliver tumor antigens and adjuvants (IFN-γ and TNF-α) to DCs, resulting in DC activation, DC migration to the draining lymph nodes, and activation of tumor-specific T cells capable of cancer cell killing." (PMID 36854774, 2023). "However, higher levels of growth upon contact with tumor cells and increased IFN-γ and TNF-α levels were observed." (PMID 38328405, 2023). "On the contrary, a study of 97 HCC patients showed that patients with advanced disease (stage III and IV, according to the TNM classification) did not have a higher expression of TNF-α in HCC tumor samples compared with those with TNM stage I and II." (PMID 37958479, 2023). "The balance of tumor immunity is towards antitumor due to the upregulated expression of tumor antigens, FAS, TRAIL receptors, MHC class I on tumor cells and granzymes, IL-1, IL-12, TNF-α, IFN-α/β/γ, and perforin in TME." (PMID 37345046, 2023). "Indeed, anti-tumor activity mediated by TNFα derived from MCs and its cytotoxic activity was demonstrated by exploiting the WEHI-164 TNFα-sensitive cell line." (PMID 37376140, 2023). "Furthermore, when combined with PD-1 mAb, the treatment resulted in more tumor-infiltrating CD8+ T cells and greater secretion of tumor-killing factors like IFN-γ, TNF-α, and GZMB." (PMID 37397393, 2023).
tumor (continued). "TNF-alpha, which is a ubiquitous TME cytokine secreted by tumour cells and macrophages, may promote metastasis of breast and other cancers." (PMID 38332913, 2023). "Additionally, previous research has also suggested a positive correlation between TNF-α and colorectal cancer due to its ability to increase COX-2 expression, damage DNA, and stimulate tumour angiogenesis." (PMID 37742025, 2023). "TNF-α promotes the accumulation of MDSCs in tumor tissue, which are considered important negative immune regulators." (PMID 37958479, 2023). "TNF-α concentrations in excess of 36 pg/mL have been reported in the circulation of patients with CRC and levels of up to 25 pg/mL have been reported in CRC tumour tissues." (PMID 36765584, 2023). "In this study, we aimed to investigate the effects of anti-TNFα mAb on tumor progression and TME in the absence of intestinal inflammation using an allogeneic immune response orthotopic transplantation model of CT26, a CRC cell line derived from BALB/c mice." (PMID 36996146, 2023). "Moreover, TNF-α obviously elevated D2-40 and VEGFC protein expressions in tumor tissues, promoting lymphangiogenesis and lymphatic metastasis in vivo." (PMID 37124061, 2023). "TGFβ and TNFα in TME are very important in the formation and development of tumor." (PMID 36865554, 2023). "In contrast, JAK-STAT, TGFb, and TNF signalling are elevated in OVE16 and STOSE cell lines, which may be ideal to model tumours with high levels of inflammation and chemoresistance." (PMID 37957414, 2023). "Mast cell proteases significantly influence not only inflammation but also angiogenesis, thus affecting tumor growth and progression by acting on immunosuppression, release of the proangiogenic cytokines VEGF, IL-18, and TNF-α, mitogenic factors, and extracellular matrix degradation." (PMID 37185713, 2023). "TNF-α signaling through TNFR2 on MDSCs has been identified as a prominent mechanism in the accumulation, persistence, and survival of MDSCs in tumor sites, and also for their ability to exert suppressive and tumor promoting functions." (PMID 37537225, 2023). "Inflammatory responses occur at the early stage after LITs, increasing the permeability of tumor vessels and promoting the injured tumor cells to produce chemokines (e.g., CCL2, CCL3, CCL4, CCL8, etc.)and proinflammatory cytokines (e.g., TNF-α, IL-1, IL-6, IL-17, etc.)." (PMID 36831664, 2023). "Additionally, the remaining macrophages detected in the tumor from the VSSP-treated mice exhibited an M1 phenotype characterized by an increased expression of CD80, IL-12 and TNFα." (PMID 37055829, 2023). "Omeprazole has been proved to inhibit the activity of MAPK and NF‐κB and subside with the downregulation of TNF‐α, IL‐6 and SOD2 which may suppress the growth of tumours." (PMID 35961680, 2023). "Mondini and colleagues confirmed that radiotherapy can promote the secretion of CCL2 by tumor cells and induce the accumulation of CCR2+ Tregs and CCR2-dependent macrophages which can produce TNF-α, then TNF-α induces Tregs activation and decreases the efficacy of radiotherapy." (PMID 36845095, 2023). "In previous studies, it was found that PD-L1 expression in tumor cells could be upregulated by interferons (IFN) or cytokines, such as tumor necrosis factor (TNF)." (PMID 37240068, 2023). "In two-stage carcinogenesis experiments with mouse skin, TNF-α−/− mice treated with DMBA plus okadaic acid showed no tumors for up to 19 weeks, whereas in similarly treated TNF-α+/+ mice the percentage of tumor-bearing mice was 100%." (PMID 37097392, 2023). "Interestingly, subsequent studies have found that tumour necrosis factor‐α (TNF‐α) and TNF related apoptosis‐inducing ligand, including tumour necrosis factors, can activate both necroptosis and conventional apoptosis." (PMID 36583248, 2023).
tumor (continued). "It decreases the tumorigenesis marker such as matrix metallopeptidase 3 (MMP-3), interleukin-6 (IL-6), tumor necrosis factor-α (TNF-α), and proliferating cell nuclear antigen (PCNS), and stem cell markers including CD133 leading to reducing tumor size of REM134 canine mammary carcinoma." (PMID 38188673, 2023). "TNF-α plasmid (also known as the TNF erode), along with radiotherapy, and they observed marked tumor response, without encountering local or systemic toxicity." (PMID 36418230, 2023). "However, it is important to mention that both TGF-β and TNF-α are actively secreted during the inflammation stage and have been shown to inhibit AGR2 expression in tumor systems." (PMID 37175601, 2023). "Cell death of Daoy and UW228 was significantly induced by treatment with targeted RGD4C.TPA.TNFα as compared to mock targeted or nontargeted vectors, which did not induce any significant tumor cell death." (PMID 37331004, 2023). "Third-generation EpCAM-CAR-T cells were cytotoxic to target cells and induced lysis in them in an EPCAM-dependent manner leading to notable regression of tumor growth and secretion of cytotoxic interferon gamma (IFN-γ) and tumor necrosis factor alpha (TNF-α) in the MDA-MB-231 model." (PMID 37457288, 2023). "In addition, flow cytometry analysis of tumor-infiltrating immunocytes indicated significantly decreased IFN-β and TNF-α levels in the Gpx4-KD group." (PMID 38065948, 2023). "Second, to reveal potential links to TNF-α, we examined the impact of TNF blockade in the migration assay and found that anti-TNF antibody reduced migration in cocultures of tumor cells with supernatants from NLDM-derived AMs with or without enhanced β-catenin expression (left)." (PMID 37092550, 2023). "Next, upon detection of tumors in mice, the tumor‐bearing mice were intravenously injected with 5×1010TU/mouse of targeted RGD4C.TPA.TNFα or nontargeted TPA.TNFα vectors expressing TNFα under the control of CMV promoter." (PMID 37331004, 2023). "The expression levels of monocyte chemokines (csf-1 and ccl-2) in tumor cells of mice treated with EGCG were lower, and the cytokine was skewed from M2-to M1, which was manifested as the decrease of IL-6 and TGF-β, and the increase of TNF-α." (PMID 37560476, 2023). "The TNF (tumour necrosis factor), also known as TNFα, is a cytokine that can directly kill tumour cells and has no obvious cytotoxicity to normal cells." (PMID 36766339, 2023). "Tumor cells secrete various factors that stimulate osteoclast-mediated bone resorption, and there are studies showing that IL-1, IL-6, IL-8, tumor necrosis factor (TNF)-α, and transforming growth factor (TGF)-β are secreted by tumor cells and contribute to osteoclast-induced bone resorption." (PMID 36795736, 2023). "We have previously demonstrated that in the early-stage CT26-bearing tumor model after RFA, the percentages of the total infiltrating CD8+T cells, or the percentages of IFN-γ- or TNF-α-expressing CD8+T cells in the tumor tissues, are significantly increased in contrast to the non-ablated groups." (PMID 36900218, 2023). "Recombinant human TNF-α (rhTNF-α) and thiolated PEG were concurrently bound to the surface of 27 nanometer colloidal gold particles to generate CYT-6091 (AurimuneTM), a revolutionary tumor-targeting nanomedicine." (PMID 37483629, 2023). "Using this coculture model, we found that incubation with CMTM6-knockout tumor cells significantly reduced the expression of T cell activation markers (CD137 and CD69) and T cell effector cytokines (IL-2 and TNFα) compared to wild-type and CMTM6-reconstituted tumor cells." (PMID 37683639, 2023). "Antibody-mediated bridging between FcγRIIIA/FcγRIIA on NK cells/phagocytes and target antigen on the tumor cells can trigger the release of IFNγ, TNFα, IL6, and MCP-1 during the ADCC reaction and NK cell–secreted IFNγ and TNFα were shown to potentiate the NK-mediated target cell lysis." (PMID 37067909, 2023).